APC (APC regulator of Wnt signaling pathway)
Diseases named in the same sentence as APC in open-access papers (continued):
Sharing a sentence is not in itself a finding about the gene and the disease.
tumor (continued). "Specifically, their study revealed that the loss of GN hormone expression, but not the GC-C receptor, occurs at the earliest stages of adenomatous polyposis coli (APC)-dependent tumor transformation in both humans and mice." (PMID 37927469, 2023). "The data are consistent with a previous finding whereby restoring APC function promotes tissue differentiation and tumor regression." (PMID 36669491, 2023). "In summary, this study demonstrates that actomyosin-mediated cell mechanics drive tumor cell self-renewal and tumorigenicity via cytoskeleton/APC/Wnt/β-catenin/Oct4 signaling, which are clinically relevant and associated with patient survival." (PMID 37746658, 2023). "In approximately 85% of colon cancers, the adenomatous polyposis coli (APC) gene, a critical tumor suppressor, undergoes deletion or inactivation." (PMID 38156313, 2023). "The protein levels of MLCK and APC increased from low to high differentiation tumors, while nuclear localization of β-catenin decreased along with tumor differentiation." (PMID 37746658, 2023). "Region-specific APC mutations have been associated with differential WNT/β-catenin transcriptional activity and tumor susceptibility." (PMID 36669491, 2023). "The increase in tumor-promoting gut bacteria in the mouse model of colorectal cancer induced by the APC gene upregulated IL-1R1 expression on T cells, which in turn stimulated the production of IL-17 and IL-22, thereby promoting tumor progression." (PMID 37680632, 2023). "Nevertheless, apart from how YAP influences colonic epithelial regeneration and neoplasia, most studies are consistent with the direct regulation of Hippo signaling components by APC and GSK-3." (PMID 37759479, 2023). "This hyper-methylation in APC promoter can have a central function in the tumor initiation and progression in GC via the stimulation of Wnt signaling." (PMID 37386429, 2023). "This revealed increased levels of dihydroorotate, and other intermediates of de novo pyrimidine synthesis in APC and APC KRAS tumours." (PMID 37580540, 2023). "The results demonstrated that the environmental disruption of the circadian clock accelerated the tumour burden in the APC mutant GEMM, as well as patient-derived organoids (PDOs), which highlights the importance of the circadian clock in the intestine." (PMID 36766788, 2023). "Candidate gene-based studies have shown that hypermethylation of tumor suppressor genes, including p16, MGMT, RASSF1A, and APC, occurs early in neoplasia and rises with carcinoma development, implicating these processes in disease onset and progression." (PMID 38001653, 2023). "To test the relevance of our findings in a tumour model, we performed endoscopy-guided injection of 4-OH-tamoxifen in the colonic submucosa of APC and APC KRAS mice." (PMID 37580540, 2023). "CRC stem cells contain mutations in the Wnt/β-catenin signaling pathway, most often in the APC tumor suppressor, that drive target gene expression through TCF/β-catenin complexes." (PMID 36833408, 2023). "used CRISPR engineering to knock out ZAP and APC and found that the deletion of both synergies promotes tumor growth." (PMID 37020597, 2023). "In blocking the WNT signaling pathway, APC protein plays a vital role in inhibiting cell proliferation and survival (by evading apoptosis); tumor processes stimulated by it; and cell migration, adhesion, differentiation, and chromosome segregation." (PMID 37509254, 2023). "For example, the APC gene has tumor suppressor activity and an antioncogenic role with regard to Wnt signaling canonical pathways, which are known as one of the main factors that indicate its importance as a tumor suppressor." (PMID 37901797, 2023).
tumor (continued). "Adenomatous polyposis coli (APC) is a tumor-suppressor protein that induces the degradation of oncogenic beta-catenin and negatively regulates Wnt signaling." (PMID 38139220, 2023). "The APC protein is a component of the β-catenin destruction complex and plays a critical role in maintenance of the stem cell niche and tumour suppression in the intestinal epithelium." (PMID 37580540, 2023). "Human EB1 was originally cloned using as a bait the COOH terminus of adenomatous polyposis coli (APC), a tumour suppressor." (PMID 37520527, 2023). "Tumour hypermethylation (~ 50%) of the APC promoter region was present in all three MLH1 methylated EOCRCs similar to MLH1 epimutation CRCs (mean β = 0.57) and LS-CRCs (0.33) but higher than the MMR-proficient (0.19) and sporadic MLH1 methylated CRCs (0.16)." (PMID 37270516, 2023). "The study was designed to knock down the PD-1 of tumor lymphocytes and PD-L1 of tumor cells or possibly APC through the siRNA system to boost tumor-specific lymphocyte responses in an ex vivo model." (PMID 37735656, 2023). "Targeted data analysis showed that SAM and SAH levels were significantly increased in tumours compared to paired NAT of both APC and APC KRAS mice." (PMID 37580540, 2023). "APC is a classical tumor suppressor gene and GSK-3 is a protein kinase that phosphorylates the canonical Wnt signaling effector β-catenin." (PMID 37489330, 2023). "Administration of R-IMPP to ApcMin/+KrasG12D/+Villin-Cre (50 mg/kg, i.p., 3 times/week) also significantly suppressed tumor number (P < 0.01) and load (P < 0.01), validating its efficacy in spontaneous APC/KRAS-mutant CRC." (PMID 35803966, 2022). "The combination of both molecules (pT/A) thus leads to a significant stabilization of APC/C-substrates, prevents mitotic exit in tumor cells and promotes apoptosis." (PMID 35832196, 2022). "Long considered a canonical tumor suppressor, APC can inhibit excessive tumor cell proliferation by regulating Wnt signaling." (PMID 35486034, 2022). "A recent study showed that EB1 expression is increased in human tumor samples, whereas APC expression in the same sample is reduced." (PMID 35885015, 2022). "APC is a tumor suppressor gene, and the APC protein binds to the beta-catenin complex, leading to negative regulation of the Wnt signaling pathway." (PMID 36499289, 2022). "We show here that the tumor suppressor and cell polarity regulator APC is key for T cell adhesion and migration." (PMID 35417240, 2022). "Our results suggest that APC expression is correlated with immune infiltration and participates in tumor regulation, but it has different regulatory effects among tumors." (PMID 35303016, 2022). "Depletion of ANAPC5 exhibited a synthetic lethal interaction with paclitaxel in NSCLC cells, suggesting enhanced sensitivity to APC/C inhibition in the tumor cells." (PMID 35804895, 2022). "In two patients (2/22, 9%), APC promoter methylation was detected both in the primary tumor and in the corresponding plasma-cfDNA." (PMID 35538556, 2022). "During tumor progression, specific gene promoters and CpG islands are hypermethylated, leading to silencing of genes including tumor-suppressor genes like APC and RASSF1." (PMID 35272673, 2022).
tumor (continued). "The adenomatous polyposis coli (APC) gene, as a tumor suppressor gene, directly participates in the Wnt signaling pathway and regulates β-catenin expression in order to regulate cell proliferation." (PMID 35736152, 2022). "The tumor suppressor APC is a key component of the β-catenin destruction complex that can interact directly with β-catenin in the nucleus to negatively regulate canonical Wnt signaling and control cell proliferation, survival, differentiation, and migration." (PMID 35204808, 2022). "The presence of well-known mutations reported in genes that commonly occur in EAC, known as driver mutations like ARID1A, CDKN2A, KRAS, APC, SMAD4, and PI3KCA, and a high tumor mutation burden (TMB) level makes EAC a highly heterogeneous disease." (PMID 35328735, 2022). "Meanwhile APC reduces HIF-1α mRNA in a β-catenin l-dependent manner, implying that HIF-1α downregulates APC further improves tumor cell survival under hypoxia." (PMID 35928881, 2022). "In the larger-sample-size TCGA cohort, it also showed a higher mutation frequency of APC and PCBP1 in KRAS-Mut samples than in WT tumor samples (adjusted chi-square test, P < 0.05)." (PMID 35836817, 2022). "The initial APC and KRAS mutations drive effective proliferation and growth, while inactivation mutations in Smad4 prevent differentiation during tumor progression." (PMID 35273961, 2022). "The phosphorylation levels of T1438 and S2449 of APC are opposite differentially expressed in various tumor cells." (PMID 35303016, 2022). "Loss of APC in intestinal cancer cells or loss of PTEN in melanoma cells has also been shown to induce DKK2 expression, which coordinates tumor immune evasion via LRP5 and suppression of STAT5 signaling." (PMID 35204808, 2022). "In short, the change in survival is only related to a part of the tumor cases in our research, suggesting that the APC gene on the survival and prognosis of patients is tumor-type dependent and can provide reference for basic and clinical research." (PMID 35303016, 2022). "Simvastatin treatment significantly inhibited transcript levels of LRP6 (1.69‐fold), AXIN2 (3.33‐fold) and Cyclin D1 (1.59‐fold), while we found a higher expression of the tumour suppressor APC levels compared to control." (PMID 35118811, 2022). "APC is low expressed in most tumor tissues, and there is a significant correlation between the expressed level of APC and the main pathological stages as well as the survival and prognosis of tumor patients." (PMID 35303016, 2022). "The APC gene is a tumor-suppressor gene and plays an important role in cell proliferation, migration, adhesion, differentiation, and chromosome aggregation in CRC." (PMID 35617032, 2022). "Upon review of additional tumor gene subpopulations, APC gene status was identified as a key prognostic indicator of EGFR-inhibitor efficacy." (PMID 35685436, 2022). "Except for one tumor specimen (subject 43), APC and CTNNB1 genetic aberrations were mutually exclusive." (PMID 34986841, 2022). "In contrast, APC mutation, referred to as characteristics of CIN subtype (CINWntUp) in GSE39582 dataset, was mainly enriched in FAC1-like tumor cells." (PMID 35342352, 2022). "Wnt signaling is activated by the inactivation of adenomatous polyposis coli (APC), which is a tumor suppressor, and the activation of β-catenin, which is a proto-oncogene." (PMID 36555115, 2022). "METTL3 promotes tumor development by decreasing APC gene expression mediated by APC mRNA m6A-dependent YTHDF binding." (PMID 36249071, 2022).
tumor (continued). "Taken together, these data indicate that APC-mutant CRC tumor cells are differentially and exquisitely sensitive to treatment with statin compounds, both in vitro and in vivo." (PMID 35712511, 2022). "The destruction complex consists of proteins Axin, Adenomatous polyposis coli (APC), and Wilms tumor gene on the X chromosome (WTX), casein kinase 1-α (CK1α), glycogen synthase kinase 3-β (GSK-3β), and other factors." (PMID 35116092, 2022). "In this study, we took advantage of a model of APC-driven intestinal tumorigenesis to demonstrate that glucose metabolism promotes tumor initiation by controlling stem cell activity and TICs in the intestine." (PMID 35314684, 2022). "The studies showed that normal cells treated with exosomes from untreated tumor cells had the lowest expression of the APC gene." (PMID 36012171, 2022). "hTid-1 proteins being members of the DnaJ protein family, are essential components of the Hsp70/Hsc70 chaperone machinery and act as an important link between the function of chaperone machines, APC-mediated Wg/Wnt signaling and tumor development." (PMID 35854300, 2022). "In this model, most mutations, including APC and KRAS, occur less often than in sporadic CRC and at later stages of tumor evolution, where they promote cytokine secretion, tumor growth, and angiogenesis via the NF-κB, IL-6/STAT3, or IL-23/Th17 pathways." (PMID 35884974, 2022). "This is important to ensure the controlled growth and proliferation of the cells, and hence hTid-1 plays the role of a tumor suppressor along with APC." (PMID 35854300, 2022). "We also found that afatinib, a pan-HER TKI, inhibited tumor growth of HER2 G776S-transfected COLO-320 cells with mutant APC." (PMID 35654814, 2022). "The APC (Adenomatous polyposis coli) and FBXW7 (F-Box and WD repeat domain containing 7) genes are critical tumour suppressors and are amongst the most commonly mutated genes in CRC." (PMID 35046388, 2022). "Taken together, the current state of knowledge provides a compelling rationale to further pursue on the role of the APC/C in tumor development and treatment." (PMID 35832196, 2022). "APC is a tumor suppressor that indirectly regulate a number of key genes involved in cell proliferation." (PMID 35399006, 2022). "The expression levels of NRIP1 and APC were significantly lower in tumor tissues than normal samples." (PMID 35473611, 2022). "The action of β-catenin is influenced by the adenomatous polyposis coli protein (APC), a tumor suppressor, and E-cadherin." (PMID 35681707, 2022). "As a typical tumor suppressor gene, APC can negatively regulate the canonical WNT signaling pathway and participate in the regulation of cell-cell adhesion and cell migration by recognizing and activating Asef." (PMID 36204371, 2022). "Loss-of-function mutations of APC have been shown to induce the accumulation of β-catenin and activate TCF signaling pathway, thus promoting tumor evolution." (PMID 36439454, 2022). "The APC/C either has an oncogenic function after binding to its co-activator Cdc20, or works as a tumor suppressor when bound to Cdh1." (PMID 35832196, 2022). "At the top of the table are given the states of the integrin, RTK, and Wnt receptors, while the signals from E‐cadherin and tumor suppressors, APC and NF1, are indicated at the right and left of the table, respectively." (PMID 35132721, 2022).
tumor (continued). "Tumor organoids were generated from intestinal tumor tissues isolated from APC/KRAS compound mutant mice and cultured in 3D Matrigel with modifications." (PMID 35541903, 2022). "Efforts have been converged for the design of the APC-Asef inhibitor and it avoids the development of neoplasm." (PMID 33670371, 2021). "Differently from APC, however, R/Z tumours still depend on a source of WNT ligands and are sensitive to PORCN inhibitors, small molecules that prevent WNT secretion and inhibit paracrine signalling." (PMID 33938624, 2021). "The regulation of DNMTs and APC by piR-823 were validated in the tumor samples from the xenograft model." (PMID 33791297, 2021). "It occurs generally by DNA hypermethylation at the 5′-CG-3′ (CpG) dinucleotide in the promoter region, resulting in gene silencing and the function loss of some tumor suppressor genes such as MLH1, APC, MCC, MGMT, and several others." (PMID 34326875, 2021). "The absence of known Wnt regulators among our top candidates was surprising and thus we tested specific KO of APC and Axin2, two tumor suppressors which are core regulators of Wnt signaling." (PMID 34552058, 2021). "In DLBCL, circAPC suppresses tumor cell proliferation by sponging miR-888, upregulates APC expression, and eventually inactivates Wnt/β-catenin pathway." (PMID 34852843, 2021). "The tumor 1 (70% tumor content) had following mutations: KRAS p.G13D (allelic fraction (AF) = 35.27%), APC p.R283*(AF = 32.94%) and PIK3CA p.E545K(AF = 4.34%)." (PMID 34600484, 2021). "Desmoid tumors frequently have mutations in APC or CTNNB1; however, mechanisms driving functional activation and tumor growth are not well understood." (PMID 34590610, 2021). "Likely, the final tumor weighs of xenograft assay also displayed consistent results with tumor growth curve both in APC-overexpressed Hep3B and Huh1 cells." (PMID 34344448, 2021). "Previous studies suggested that COL11A1 regulates tumor progression through the APC/beta-catenin pathway, and inhibits apoptosis by modulating the NFkB pathway." (PMID 33428592, 2021). "Promoter hypermethylation/silencing of the Adenomatous Polyposis Coli (APC) and Ras-association Domain Family Member 1A (RASSF1A) tumor suppressor genes have been demonstrated to be a common epigenetic change in parathyroid tumors." (PMID 34681865, 2021). "The tumor frequently harbors germline or somatic mutation of adenomatous polyposis coli (APC) or somatic mutation of CTNNB1, both of which lead to the accumulation of β-catenin in cytoplasm and nucleus of tumor cells, which can be detected by IHC." (PMID 35008368, 2021). "-miRNA-191 downregulated TET1 expression, an enzyme that is involved in the removal of methylated DNA in the loci of adenomatous polyposis coli (APC) and other tumor suppressor genes." (PMID 33800944, 2021). "Intriguingly, a wide EHMT2 bind peak was found around the promoter region of APC, a tumor suppressor that promotes the rapid degradation of β-catenin to negatively regulate Wnt–β-catenin signaling (circled by a red rectangle)." (PMID 34344448, 2021).